FGF21 (fibroblast growth factor 21)
Diseases named in the same sentence as FGF21 in open-access papers (continued):
Sharing a sentence is not in itself a finding about the gene and the disease.
cardiac hypertrophy (continued). "Fibroblast growth factor 21 (FGF21), a polypeptide ligand promoted glucose homeostasis and lipids metabolism, was recently reported to attenuate cardiac hypertrophy." (PMID 27650781, 2016). "Cardiac hypertrophy is also more enhanced in response to the infusion of isoproterenol in FGF21 knockout mice." (PMID 27803896, 2016). "Mechanistic studies indicated that FGF21 prevented cardiac hypertrophy by activating mitogen-activated protein kinase (MAPK) signaling via activation of FGFR1c/β-klotho." (PMID 27247947, 2016). "FGF21(−/−) mice exhibit enhanced induction of cardiac hypertrophy markers and pro-inflammatory pathways." (PMID 27690014, 2016). "Recently, cardiac hypertrophy was reported to induce FGF21 gene expression in the cardiomyocytes of mouse, and this was subjected to transcriptional regulation of the hepatic silent mating type information regulation 2 homolog 1/PPARα pathway." (PMID 27247947, 2016). "Experimental in vivo and in vitro studies in mice have shown that FGF-21 protects against cardiac hypertrophy." (PMID 27690014, 2016). "The expression of antioxidant genes in response to the lipopolysaccharide (LPS)-induced stimulation of pro-inflammatory pathways or isoproterenol-induced cardiac hypertrophy is decreased in the hearts of FGF21 knockout mice." (PMID 27803896, 2016). "FGF21 has been demonstrated to protect against cardiac hypertrophy, cardiac inflammation, and oxidative stress." (PMID 26379627, 2015). "In response to isoproterenol infusion, a standard model used to induce cardiac hypertrophy, heart size, and cardiomyocyte volume are increased to a larger extent in FGF21-knockout mice compared with control mice." (PMID 26379627, 2015). "FGF21 expression in the heart is induced in response to cardiac insults, such as experimental cardiac hypertrophy and myocardial infarction in rodents, as well as in failing human hearts." (PMID 26379627, 2015). "Our research group obtained the first data that addressed this question showing that FGF21 is expressed in and secreted by cells of the heart in response to different cardiac stress stimuli, such as cardiac hypertrophy and myocardial infarction." (PMID 26379627, 2015). "In summary, current data support the idea that FGF21 acts directly on cardiac tissue to prevent the development of cardiac hypertrophy, reduce infarct damage, and attenuate the development of diabetic cardiomyopathy in animal models." (PMID 26379627, 2015). "Treatment with recombinant FGF21 reverses cardiac hypertrophy in Fgf21 KO mice and cultured cardiomyocytes." (PMID 26594197, 2015). "Mouse models of experimentally induced cardiac hypertrophy and myocardial infarction also showed significant increases in FGF21 expression in the heart." (PMID 26379627, 2015). "Further evidence for a putative role of PPARα in cardiac hypertrophy comes from studies on fibroblast growth factor 21 (FGF21), which is expressed in and released by cardiomyocytes through a PPARα - dependent mechanism." (PMID 24938300, 2014). "Exaggerated cardiac hypertrophy and dysfunction were observed in Fgf21 knockout mice in response to the infusion of isoproterenol." (PMID 25071723, 2014). "In contrast, administration of FGF21 significantly prevented lipotoxicity induced kidney weight increase (a feature of renal hypertrophy) and renal dysfunction." (PMID 24349242, 2013). "FGF21 prevents cardiac hypertrophy by activating MAPK signaling through the activation of FGFR1c with β-Klotho as a co-receptor." (PMID 24046748, 2013). "In response to isoproterenol infusion, cardiac hypertrophy was more enhanced in Fgf21 knockout mice." (PMID 24046748, 2013). "FGF21 prevents cardiac hypertrophy by activating MAPK signaling through the activation of FGFR1c with β-Klotho." (PMID 24046748, 2013). "Results of a recent study suggested that FGF21 prevented cardiac hypertrophy via suppression of inflammation." (PMID 24349242, 2013).
cardiac hypertrophy (continued). "FGF21 attenuates inflammation and oxidative stress, inhibits cardiac hypertrophy and collagen synthesis, and may counteract myocardial remodelling, cellular senescence, apoptosis, pyroptosis, and ferroptosis of cardiomyocytes." (PMID 41464745, 2025). "FGF21 also has the ability to influence cardiac hypertrophy, but it is known that FGF21 levels decrease significantly during the first two trimesters of pregnancy, while cardiac output begins to increase in the first trimester and continues to do so into the third trimester." (PMID 39452290, 2024). "Moreover, the protective effects of FGF21 on cardiac hypertrophy, fibrosis, and apoptosis were suppressed by SIRT1 elimination in Ang II-induced hypertensive mice." (PMID 37576954, 2023). "FGF21 has substantial promise as a novel biomarker as its circulating level gives an insight into several pathophysiological processes, such as oxidative stress, cardiac hypertrophy, and inflammation, that are involved in HF." (PMID 36028609, 2023). "Previous studies showed that the heart synthesizes and releases FGF21, and FGF21 knockout mice exhibit increased cardiac hypertrophy and proinflammatory cytokine production in response to isoproterenol infusion, suggesting the cardioprotective role of FGF2111,37." (PMID 35513524, 2022). "Exogenous FGF21 could attenuate oxidative stress in cultured cardiomyocytes in vitro and prevent cardiac hypertrophy and myocardial infarction in mice." (PMID 36618930, 2022). "Besides, deletion of FGF21 has been shown in severe myocardial damage, and the administration of FGF21 has been proved to prevent ventricular hypertrophy and adverse cardiac remodeling after myocardial infarction (MI) mice model." (PMID 36180826, 2022). "βOHB stimulation reduced the expression of atrial natriuretic peptide (ANP), B-type natriuretic peptide (BNP), transforming grow factor-β (TGF-β) and connective tissue growth factor (CTGF), suggesting the protective role of βOHB and FGF21 against cardiac hypertrophy." (PMID 35513524, 2022). "Systemic FGF21 elevation in vivo resulted in concentric cardiac hypertrophy." (PMID 35513431, 2022). "Here we consider the novel hypothesis that, despite its ability to promote myocyte survival, the elevation of FGF21 in T2D is not beneficial, but deleterious, such that in the context of T2D elevated FGF21 promotes pathological concentric cardiac hypertrophy." (PMID 35513431, 2022). "We next examined the effects of βOHB and FGF21 on the molecular signatures of cardiac hypertrophy." (PMID 35513524, 2022). "A previous study found that cardiac hypertrophy was more severe in FGF21 knockout mice, while this trend could be reversed after supplied with FGF21 in both FGF21 knockout mice and cultured cells." (PMID 34567165, 2021). "Indeed, FGF21 has been shown to be expressed in the heart as part of the stress response to cardiac hypertrophy, cardiac remodeling, and myocardial infarction." (PMID 35046901, 2021). "In addition, FGF-21 prevented the development of cardiac hypertrophy by activating MAPK signaling through the activation of FGF-R1c with β-klotho as a coreceptor." (PMID 33520013, 2021). "FGF21 reverses cardiac hypertrophy in FGF21 knockout mice and cultured cardiomyocytes." (PMID 27803896, 2016). "Additionally, FGF21 prevented cardiac hypertrophy by promoting multiple antioxidant genes expressions (e.g., uncoupling proteins 2 and 3, also superoxide dismutase-2) and inhibiting the formation of reactive oxygen species in an autocrine manner." (PMID 27247947, 2016). "FGF21 may act as an endocrine as well as an autocrine factor to suppress oxidative stress and prevent cardiac hypertrophy." (PMID 27650781, 2016). "However, administration of recombinant FGF21 significantly prevented isoproterenol-induced cardiac hypertrophy damage in mice." (PMID 27247947, 2016). "While FGF16 and FGF21 may prevent cardiac hypertrophy and fibrosis, FGF2 and FGF23 display the opposite effect." (PMID 27184924, 2016).
cardiac hypertrophy (continued). "Although the precise underlying signal transduction mechanisms caused by individual injuries remain to be established, FGF21-mediated protection against DCM development, myocardial I/R injury and isoproterenol (ISO)-induced cardiac hypertrophy have been demonstrated." (PMID 27941647, 2016). "Thus, this study indicates that FGF21 exerts protective effects against cardiac hypertrophy through a mechanism involving PGC1α." (PMID 26379627, 2015). "Cardiomyocytes produced and secreted FGF21, indicating that FGF21 is a myokine that may protect against cardiac hypertrophy in an autocrine/paracrine manner." (PMID 25071723, 2014). "FGF21 reversed cardiac hypertrophy in Fgf21 knockout mice and cultured cardiomyocytes." (PMID 24046748, 2013). "Further prospective studies with larger sample sizes are needed to determine whether FGF21 is related to myocardial hypertrophy in patients with CKD." (PMID 21525989, 2011). "Similarly, FGF21 reduced angiotensin II (Ang II)-induced myocardial hypertrophy through SIRT1." (PMID 31498116, 2019). "In brown adipose tissue, upon adenosine binding to the surface receptor A2AR, released FGF21 can be upregulated by phosphorylating AMPK and PGC-1 α against cardiac hypertrophy." (PMID 37416922, 2023). "The expression of fibroblast growth factor 21 (FGF21), a cardioprotective factor, is increased in patients with cardiac hypertrophy but fails to prevent heart failure." (PMID 41173187, 2025). "While short-term FGF21 elevation can be cardio-protective, we find that in type 2 diabetes (T2D) in mice, where serum FGF21 levels are elevated, FGFR4 activation induces concentric cardiac hypertrophy." (PMID 35513431, 2022). "FGF21 is not the only member of the FGF family that can induce cardiac hypertrophy via ERK1/2 signaling." (PMID 35513431, 2022). "Mice lacking FGF21 showed increased rates of cardiac hypertrophy and inflammation and decreased capacity of fat oxidation." (PMID 36618930, 2022). "A recent notable study showed that mice lacking FGF21 had enhanced cardiac hypertrophy; however, treatment with FGF21 in mice protected against this hypertrophic response, suggesting the cardioprotective role of FGF21." (PMID 28582462, 2017). "Moreover, FGF21-mediated protection through ERK1/2 activation against DCM development, myocardial I/R injury, and ISO-induced cardiac hypertrophy has been demonstrated." (PMID 27941647, 2016). "Thus, while FGF23 may be an important mediator of cardiac hypertrophy in CKD, FGF21 may have an especially important role in the induction of concentric hypertrophy in diabetic cardiomyopathy." (PMID 35513431, 2022). "On the one hand ERK1/2 activity is thought to be involved in development of cardiac hypertrophy while on the other hand ERK1/2 signaling might have beneficial effects on abnormal healing and cardiac dysfunction via regulation of Fibroblast growth factor 21 (FGF21) signaling." (PMID 33184414, 2020).
coronary heart disease (60 papers, 2010 to 2025). "A meta-analysis revealed that there was a significant association between FGF21 level and coronary artery disease (HR 1.29 [95% CI 1.06–1.55])." (PMID 40356318, 2025). "Recently, our laboratory results indicated that serum FGF21 levels significantly increase in patients with coronary heart disease and are associated with relevant risk factors including abnormal lipid profiles and glucose metabolism." (PMID 35463746, 2022). "In analyses of cardiovascular diseases, the FGF21 rs838133 G allele was strongly associated with a reduced risk of venous thromboembolism, and had suggestive inverse associations with coronary artery disease, heart failure, and ischemic stroke." (PMID 33946944, 2021). "There is strong evidence suggesting a significant association between elevated serum FGF21 levels and the development of atherosclerosis, myocardial ischemia, coronary heart disease, cardiac hypertrophy, and diabetic cardiomyopathy." (PMID 31712677, 2019). "Our previous work confirmed that serum levels of FGF-21 are increased in patients with coronary heart disease independently associated with adverse lipid profiles." (PMID 27247947, 2016). "Increased FGF21 concentrations have been linked to a higher mortality risk in patients with end‐stage kidney disease, hemodialysis patients, heart failure, and coronary artery disease." (PMID 40390366, 2025). "However, excessively high FGF21 levels are harmful in patients with CVD, and the higher the plasma FGF21 levels in patients using statins, the higher the risk of coronary heart disease development." (PMID 40076419, 2025). "A prospective cohort study of 1668 patients with coronary artery disease yielded a U-shaped correlation between serum FGF21 levels and mortality, with both higher and lower serum FGF21 levels associated with increased cardiovascular as well as all-cause mortality." (PMID 39302236, 2024). "Moreover, in our previous study we have shown that serum FGF21 is increased in patients with coronary heart disease and independently associated with adverse lipid profile." (PMID 38057786, 2023). "Therefore, further studies are needed to elucidate the impact of coronary artery disease on the association of FGF21 and HP." (PMID 37424900, 2023). "The metabolic effects associated with FGF-21 levels in several metabolism-related diseases, such as coronary artery disease, may provide diagnostic value (Cluster ID #7)." (PMID 36238554, 2022). "High serum FGF-21 levels are associated with carotid atherosclerosis and coronary artery disease." (PMID 35186330, 2022). "Moreover, FGF21 significantly predicts the incidence of coronary artery disease and all-cause and cardiovascular mortality." (PMID 34703671, 2021). "In another recent cross-sectional study of 60 patients with coronary artery disease and 129 BMI-matched controls, higher serum FGF21 levels were independently associated with pericardial fat volume after adjusting for age, sex, BMI, triglycerides and HOMA-IR10." (PMID 31712677, 2019). "One of the strengths of the study is that FGF21 levels, lipid profile, and coronary artery disease severity were evaluated simultaneously." (PMID 35510201, 2022). "Recently, serum FGF21 levels were associated with diastolic cardiac dysfunction in humans with cardiovascular diseases, such as dyslipidemic patients with coronary artery disease, but only a few reports have examined FGF21's role in heart failure." (PMID 35983184, 2022). "In our previous study, patients diagnosed with coronary artery disease by coronary angiography had higher levels of FGF21." (PMID 28821258, 2017). "Elevated serum FGF21 levels have been reported in subjects with coronary heart disease and carotid artery plaques." (PMID 26223891, 2015).
coronary heart disease (continued). "Elevated serum FGF21 levels have also been recently reported in subjects with coronary heart disease or carotid artery plaques independently of established cardiovascular risk factors, suggesting its potential role as a biomarker for atherosclerotic diseases." (PMID 26379627, 2015). "Recently, it is reported that serum FGF21 levels are increased in coronary heart disease (CHD) and FGF21 is also found in carotid artery plaques." (PMID 26223891, 2015). "This study aimed to investigate the correlation of serum FGF-21 levels and lipid metabolism in the patients with coronary heart disease." (PMID 21206918, 2010). "FGF21's precise role in the pathogenesis of coronary artery disease (CAD) remains elusive." (PMID 38333506, 2024). "However, FGF21, which has cardioprotective effects, predicts the incidence and prognosis of coronary heart disease and AMI." (PMID 36778154, 2023). "In recent clinical trials, FGF21 was proven to be an independent predictor of coronary heart disease in patients with T2DM and increased cardiovascular risks and was used as a novel biomarker to predict major adverse cardiovascular events (MACEs) in patients with STEMI after PCI." (PMID 37538793, 2023). "FGF-21 gene expression is reduced in adipose tissue from patients with multivessel coronary artery disease associated with T2DM and enhanced in adipose tissue from patients undergoing cardiac surgery, suggesting a protective effect of FGF-21 against inflammation associated with cardiac surgery." (PMID 37822930, 2023). "However, the clinical literature showed FGF21 levels paradoxically raised or unchanged in HF and coronary artery disease." (PMID 36618930, 2022). "Similarly, serum FGF21 levels were an independent predictor of incident coronary heart disease (CHD) in diabetic patients." (PMID 34703671, 2021). "High FGF21 levels predicted the incidence coronary artery disease." (PMID 30927227, 2019). "In addition, another study found that subjects with coronary artery disease had significantly higher serum FGF21 when the presence of NAFLD was taken into account." (PMID 26047614, 2015). "Fibroblast growth factor 21 (FGF21), a glucose and lipid metabolic regulator, has recently been demonstrated to be associated with cardiovascular diseases (CVD) such as carotid atherosclerosis, coronary heart disease and carotid artery plaques." (PMID 26047614, 2015). "Furthermore, the level of FGF21 on the 7th day was associated with death within 1 month after AMI; this agrees with the finding of a previous study that showed that the FGF21 level can predict morbidity and mortality in coronary heart disease." (PMID 26091256, 2015). "In contrast to our results, one study showed a U-shaped association between serum FGF21 levels and all-cause mortality among patients with coronary artery disease and another study showed FGF21 was not an independent predictor of all-cause mortality in HD patients." (PMID 37724523, 2023). "Therefore the relationship between FGF21 and coronary heart disease is of interest." (PMID 27247947, 2016). "Coronary heart disease (CHD) patients have higher blood levels of FGF21, and patients with high concentrations of FGF21 tend to have poor lipid profiles." (PMID 35369322, 2022). "This study aimed to investigate the relationship between the prevalence of coronary artery disease (CAD) and circulating FGF21 concentrations and serum testosterone in T2DM men." (PMID 35909513, 2022). "Our study is partly limited by the lack of measurements for coronary artery disease, in which serum FGF21 concentration is reported significantly higher." (PMID 38057786, 2023). "Second, our present study is limited by the lack of measurements for coronary artery disease, in which FGF21 is significantly higher." (PMID 37424900, 2023).
coronary heart disease (continued). "Previous studies have reported that fibroblast growth factor 21 (FGF21), β-klotho, mature brain-derived neurotrophic factor (mBDNF), and BDNF precursor (proBDNF) play important roles in the pathogenesis and treatment of coronary heart disease and depression." (PMID 33584362, 2020). "Previously, high levels of FGF21 were observed in patients with coronary heart disease and non-acute myocardial infarction (non-AMI)." (PMID 26091256, 2015). "The relationship between plasma levels of FGF-21 and coronary heart disease (CHD) in unknown." (PMID 21206918, 2010).